ACE (angiotensin I converting enzyme)
Diseases named in the same sentence as ACE in open-access papers (continued):
Sharing a sentence is not in itself a finding about the gene and the disease.
acute kidney injury (continued). "Three months after admission, after controlling for blood pressure with angiotensin-converting enzyme (ACE) inhibitors, the patient continued with asthenia but without evidence of hemolytic anemia and renal failure (Cr 0.8 mg/dL without proteinuria and hematuria)." (PMID 30806445, 2019). "Compared with placebo, they found that the combination of an ACE inhibitor and an ARB seemed to prevent ESRD, did not increase doubling of serum creatinine, and improved albuminuria, at the expense of an increased risk of hyperkalemia and acute kidney injury." (PMID 26954482, 2016). "Furthermore, many cases of LA are reported in patients treated with metformin when presenting acute kidney failure due to dehydration or exposure to nephrotoxic drugs such as nonsteroidal anti-inflammatory drugs (NSAID), diuretics, and angiotensin converting enzyme (ACE) inhibitor." (PMID 27034959, 2016). "Thus, given the increased activity of local RAS, controlling blood pressure by inhibiting systemic RAS via ACE inhibitors or ARBs may not be sufficient to prevent the progression of renal failure." (PMID 34289001, 2021). "Moreover, a combined approach with ACE inhibitor, ARB and statin therapy was shown to be superior to combined treatment with ACE inhibitor and ARB, and led to complete regression of proteinuria and prevention of renal failure in a rat model of passive Heymann nephritis." (PMID 20441574, 2010). "Although ACE inhibitors and ARB slows the progression of renal failure; they were not prescribed for patients with ESRD as these medications can lead to hyperkalemia." (PMID 37203939, 2023).
Hyperkalemia (179 papers, 2008 to 2026). An abnormally increased potassium concentration in the blood. "An MRA is incorporated alongside ACE inhibitors and beta-blockers to further reduce mortality and morbidity, though close monitoring is advised for those at risk of renal impairment or hyperkalemia." (PMID 40711721, 2025). "Prescription of RAAS medications was associated with an increased risk of hyperkalaemia: ACE inhibitors (SHR 1.45, 95% CI 1.42–1.48) and ARBs (SHR 1.27, 95% CI 1.13–1.32)." (PMID 40377096, 2025). "Secondly, all three MRAs are frequently co-administered with ACE inhibitors or ARBs, which further increases the risk of hyperkalaemia." (PMID 41573738, 2025). "In patients receiving spironolactone with ACE inhibitors or ARBs, dentists should avoid high doses of ibuprofen due to the increased risk of hyperkalemia and renal impairment and choose alternative analgesics such as paracetamol." (PMID 40559158, 2025). "In some cases, the concomitant use of celecoxib with ACE inhibitors and angiotensin-II antagonists was viewed as potentially increasing the risk of nephrotoxicity and hyperkalemia, and a safe medication was recommended to resolve the risk of deterioration." (PMID 38817515, 2024). "When spironolactone and ACE inhibitors are combined, attention should be paid to the increased risk of hyperkalemia." (PMID 39455970, 2024). "Medications with hyperkalemic effects–spironolactone, amiloride, angiotensin-converting enzyme (ACE) inhibitors, and angiotensin II receptor blockers (ARBs) were involved in DDIs that were associated with laboratory deviations (hyperkalemia)." (PMID 36817138, 2023). "ACE inhibitors, ARBs, andMRAs are commonly used drugs for patients with HF that can increase serum K+levels and are common causes of hyperkalemia in patients." (PMID 39076700, 2023). "There is an elevated risk for hyperkalemia by using spironolactone and especially for taking spironolactone and an ACE inhibitor such as in three of the five patients." (PMID 33864520, 2022). "Treatment with ACE inhibitors puts individuals at increased risk of dry cough, hypotension, dizziness, and hyperkalemia by 2.66, 1.98, 1.46, and 1.24 times, respectively." (PMID 35886227, 2022). "Potassium containing foods and salt substitutes can interact with ACE inhibitors such as enalapril precipitating the risk of hyperkalaemia." (PMID 36032453, 2022). "Overall, ACE inhibitor usage was significantly associated with an increased risk of dry cough, hypotension, dizziness, and hyperkalemia, with the number needed to harm of about 28, 33, 59, and 111, respectively." (PMID 35886227, 2022). "Cotrimoxazole predisposes to hyperkalemia in elderly patients, especially during angiotensin-converting enzyme (ACE) inhibition and angiotensin receptor 1 blocker co-administration." (PMID 36678717, 2022). "Treatment with antihypertensive agents, ACE inhibitors, angiotensin receptor blockers (ARBs), a direct renin inhibitor, and MR blockers are all known to increase the risk of hyperkalemia." (PMID 33214722, 2021). "For instance, hyperkalemia patients demonstrated elevated ACE levels, which lead to an increased risk of LSCC." (PMID 33092550, 2020). "The addition of an MR blocker to an ACE inhibitor or ARB significantly increases the risk of hyperkalemia (relative risk 3.74, 95% CI 2.30–6.09, p < 0.00001)." (PMID 31239535, 2019). "In such cases, the possibility of withdrawal or reduction of drug regimens which cause hyperpotassemia (e.g. ACE inhibitors, sartans, anti-aldosterones) should be considered—after correcting the metabolic acidosis—or use of potassium-chelating resins." (PMID 29797247, 2018). "Risk of hyperpotassemia is mostly associated with taking anti-aldosterones and/or ACE inhibitors and sartans." (PMID 29797247, 2018). "A recent meta-analysis showed that aliskiren plus ACE inhibitors or ARB increases risk for hyperkalemia more than monotherapy with any of these agents." (PMID 23675422, 2013).
Hyperkalemia (continued). "Only few patients of included trials had concomitant treatment with spironolactone, probably due to the increased risk of hyperkalemia when combining ACE inhibitors, ARB's and spironolactone." (PMID 20376345, 2010). "However, some studies indicate that hyperkalemia associated with ARNI is less frequent or milder compared to ACE inhibitors or ARBs." (PMID 39937358, 2025). "The most common pDDIs were: the decrease in effectiveness and decline in kidney function caused by the use of antihypertensives with NSAIDs on a daily basis; and the risk of hyperkalemia when combining spironolactone with ACE inhibitors, ARBs, or potassium supplements." (PMID 38434703, 2024). "Moreover, even though the CPGs recommend against the dual blockade of the renin-angiotensin system due to excessive risk of hyperkalaemia, hypotension, and renal failure, a small percentage of our patients were on ACE inhibitor and ARB combination therapy." (PMID 37833402, 2023). "Moreover, aldosterone antagonists show better therapeutic benefits when used in conjunction with ARBs or ACE inhibitors, but they come with a high risk of hyperkalemia, therefore they must be recommended with caution." (PMID 35646840, 2022). "On the other hand, in patients with cardiac or renal disease, hyperkalemia is often associated with medications that suppress the renin–angiotensin–aldosterone system, such as angiotensin-converting enzyme (ACE) inhibitors, angiotensin receptor blockers (ARBs), and K-retaining diuretics." (PMID 34063969, 2021). "Hyperkalemia is also a common AE associated with ARBs and ACE inhibitors." (PMID 31239535, 2019). "This is somewhat surprising, as the combination of either ACE inhibitors or AT II antagonists with NSAIDs is associated with both diminished antihypertensive efficacy as well as an increased risk of renal impairment and hyperkalemia." (PMID 26048167, 2015). "Although teatment with spironolactone, RAAS and ACE inhibitors has been shown to provide cardiovascular benefit and reduce mortality in patients with heart failure, these drugs also have an increased risk of hyperkalemia." (PMID 25531770, 2014). "In addition these patients frequently present with risk factors for the development of hyperkalemia such as impaired kidney function and often receive a prescription of drugs increasing serum potassium levels in its own (spironolactone and ACE inhibitors)." (PMID 25480344, 2014). "In the Aliskiren Trial in Type 2 Diabetes Using Cardio-Renal Endpoints (ALTITUDE) study, the combination of the direct renin inhibitor, aliskiren, and either an ACE inhibitor or an angiotensin receptor blocker was associated with an increased risk of renal impairment, hyperkalemia, and hypotension." (PMID 24278681, 2012). "The evaluation of pharmacotherapy in the source guidelines often focused on treatment benefits and underestimated the risks, such as of adverse events, following the combination of ARBs and ACE inhibitors, or the risk of hyperkalemia following the use of aldosterone antagonists, as recently shown." (PMID 19426504, 2009). "Furthermore, spironolactone’s hormonal side effects—gynecomastia or mastodynia—were reported in approximately 10% of men, and the risk of hyperkalemia, although low within the trial, became a major concern in clinical practice, especially when combined with ACE inhibitors." (PMID 40722765, 2025). "Compared with a placebo, ACE inhibitors were significantly associated with an increased risk of dry cough (RR = 2.66, 95% CI = 2.20 to 3.20, p < 0.001), hypotension (RR = 1.98, 95% CI = 1.66 to 2.35, p < 0.001), and hyperkalemia (RR = 1.24, 95% CI = 1.01 to 1.52, p = 0.037)." (PMID 35886227, 2022). "Moreover, an intake of angiotensin-converting-enzyme (ACE) inhibitors by patients suffering from renal insufficiency was linked to the development of severe hyperkalemia, which in turn promotes the development of cardiac arrhythmias due to cardiac-myocyte depolarization." (PMID 31121936, 2019).
Hyperkalemia (continued). "Although the incidence of hyperkalemia associated with ACE inhibitor use in hypertensive patients is 1–2%, two case reports documented older adults consuming high potassium, sodium-restricted diets may be at greater risk of developing hyperkalemia with ACE inhibitor use." (PMID 29558445, 2018). "Another frequent concern is hyperkalemia resulting from the concomitant use of ACE inhibitors and potassium-sparing diuretics, especially in patients with renal impairment." (PMID 41450405, 2025). "This study was designed for new users of ACE inhibitors/angiotensin II receptor blockers, and used logistic regression to predict hyperkalaemia events within the first year, and demonstrated a c-index of 0.818 (95% CI 0.794–0.841) in external validation." (PMID 40377096, 2025). "Patients with NYHA functional class III or IV are less likely to tolerate medical therapy due to reasons such as hyperkalemia, hypotension, or renal dysfunction, which develops with higher doses of beta blockers or ACE inhibitors." (PMID 39941589, 2025). "Concomitant intake of angiotensin-converting enzyme (ACE) inhibitors with potassium-containing supplements leads to potentially serious hyperkalemia." (PMID 35409970, 2022). "We observed increased risks of hypotension (RR = 1.98) and hyperkalemia (RR = 1.24) among individuals taking ACE inhibitors." (PMID 35886227, 2022). "It was observed that hyperkalemia due to ACE inhibitor treatment was uncommon (with the number needed to harm of 111)." (PMID 35886227, 2022). "Dual therapy with ARBs and ACE inhibitors provides a little additional benefit, although the threats of hypotension, hyperkalemia, and kidney failure increase." (PMID 35646840, 2022). "Hyperkalemia is frequently observed with ACE inhibitors, ARBs, and MRAs, especially if eGFR is ≤45 mL/min/1.73 m2." (PMID 34922811, 2022). "At the beginning, a combination of an ACE inhibitor, beta blocker and diuretic was used, but shortly after the initiation of treatment, the ACE inhibitor and diuretic were discontinued due to hyperkalemia." (PMID 33008311, 2020). "Yet, the combination of ARBs and angiotensin-converting-enzyme (ACE) inhibitors is a robust approach to block RAAS; it was associated with an increased risk of adverse events, such as acute kidney injury and hyperkalemia." (PMID 33505469, 2020). "Another important aspect is that medical HF therapy in patients with CKD is frequently limited by hyperkalaemia, so patients are less likely to receive effective dosages of ACE inhibitors or ARBs." (PMID 32410664, 2020). "Hyperkalemia occurs more frequently after combined treatment with an ARB/ACE inhibitor and an MRA; thus, MRAs should be used carefully, especially when used in combination." (PMID 27843645, 2016). "Although the incidence of hyperkalemia tended to be higher among patients prescribed ACE inhibitors or ARBs concomitantly with eplerenone, it was considered within the scope of the package insert of Selara tablets." (PMID 27843645, 2016). "The role of concomitant treatments is actually the result of a previous report demonstrating that baseline potassium and concomitant angiotensin converting enzyme (ACE) inhibitor use predicted the development of hyperkalemia." (PMID 25480344, 2014). "In a retrospective cohort study of elderly patients in clinical practice, increased risks of adverse renal outcomes and hyperkalaemia were observed in those on combination therapy with an ACE inhibitor and ARB compared with those on monotherapy." (PMID 23866091, 2013). "In a community setting, retrospective cohort-based study, dual therapy with ACE inhibitor and ARB was associated with hyperkalaemia and a decrease in renal function." (PMID 23866091, 2013). "Recent studies found that combination of ACE and ARB compared with ACE inhibitors alone, was associated with significant increases in renal dysfunction and hyperkalemia, poorly tolerated, patients less adhere to combination therapy due to adverse effect." (PMID 23316345, 2012).
Hyperkalemia (continued). "On the other hand, it has also been reported that the use of ACE inhibitors induced hyperkalemia, a life-threatening complication." (PMID 19633031, 2011). "It is nonetheless not surprising that facial oedema and dry cough were the two most common, given that these two, together with hyperkalaemia, hypotension and renal dysfunction, are known and commonly reported adverse effects of ACE inhibitor use." (PMID 21556450, 2011). "Two recent meta-analyses found that add-on therapy with anti-aldosterone therapy reduces proteinuria in patients already on ACE inhibitor or ARB therapy, but this approach carries a high risk of hyperkalemia, especially in patients with advanced renal failure." (PMID 20441574, 2010). "ACE inhibitors can be used to decrease blood pressure and proteinuria, controlling hyperkalemia and renal function." (PMID 19830148, 2009). "Reasons for exclusions included intolerance or allergy to ACE inhibitors (n=3; 10.7%), renal insufficiency (n=21; 75%), and hyperkalemia (n=4; 14.3%)." (PMID 19318756, 2009). "For example, for patients at a high risk of hyperkalaemia but low-average risk of hyponatremia initiating or switching to a thiazide-type diuretic rather than ACE inhibitors/angiotensin II receptor blockers is recommended." (PMID 40377096, 2025). "These peptides offer a natural alternative to synthetic ACE inhibitor drugs, potentially without the side effects (e.g., cough, hyperkalemia) associated with long-term medication." (PMID 41375956, 2025). "Spironolactone is frequently prescribed with ACE inhibitors (e.g., perindopril and zofenopril in our dataset) and with angiotensin receptor blockers (e.g., candesartan cilexetil), combinations that increase the likelihood of hyperkalemia." (PMID 40559158, 2025). "Similarly, combined ACE inhibitor and potassium-sparing diuretic therapy necessitates proactive electrolyte monitoring to prevent hyperkalemia." (PMID 41450405, 2025). "In general, adverse effects associated with the use of these ACE inhibitors have included hypotension, hyperkalemia, or irritating nonproductive cough, while rash and angioneurotic edema are allergic symptoms." (PMID 38921258, 2024). "On the opposite side, criteria B11 (ACE inhibitors or AR blockers in patients with hyperkalemia), B8 (thiazide diuretics with current significant hypokalemia, hyponatremia, hypercalcemia or gout history) and A1 restricted to hypolipidemic drugs reached more than 90% of reduction." (PMID 38978009, 2024). "The absolute risk increase was 0.030 and 0.009, respectively; that is, with approximately 33 and 111 patients who are treated with ACE inhibitors, 1 individual patient would present with hypotension and hyperkalemia, respectively, attributable to ACE inhibitor usage." (PMID 35886227, 2022). "One study observed increased odds ratios for digoxin toxicity among patients treated with clarithromycin, for hypoglycemia in patients with co-trimoxazole combined with glyburide, and for hyperkalemia among patients who used ACE inhibitors and potassium-sparing diuretics, concurrently." (PMID 31349877, 2019). "Angiotensin-converting-enzyme (ACE) inhibitors or angiotensin II receptor blockers should be used in the presence of stable renal function, and dose should be adjusted carefully in order to prevent hyperkalemia." (PMID 31430930, 2019). "However, since ACE inhibition already carries a risk for elevated plasma K+, adding a traditional MRA further increases the risk for hyperkalemia." (PMID 29474466, 2018). "The rate of potassium level monitoring after ACE inhibitor initiation can be high, if we assume that the physicians prefer to order routine laboratory tests regardless of the event, despite their lack of knowledge of the quality indicator or relationship between the ACE inhibitor and hyperkalemia." (PMID 24130689, 2013). "Similarly, hyperkalemia or renal function deterioration often pushes clinicians to withhold ACE inhibitor/ARB therapy." (PMID 22966970, 2012).